CCL2 (C-C motif chemokine ligand 2)
Diseases named in the same sentence as CCL2 in open-access papers (continued):
Sharing a sentence is not in itself a finding about the gene and the disease.
tumor (continued). "Moreover, IL-1β induces lipolysis of adjacent adipocytes and the expression of metastasis-related and inflammatory factors such as matrix metalloproteinases (MMP), COX-2, CCL2, IL-6, TGF-β, and IL-8 which promote tumor growth and bone metastasis." (PMID 34064859, 2021). "Inhibitors of CSF1R, CCL2 and CCR2, CD47/SIRPα complex antagonists, CD40 agonist antibodies, and inhibitors of PI3Kγ and TREM2 protein are undergoing clinical evaluation for various tumor types." (PMID 34638378, 2021). "Thus, the CCL2/CCR2 axis not only regulates MPP production and therefore tumor invasion/metastasis via its action on TAMs, but also via its action on tumor cells directly." (PMID 34804061, 2021). "SPON2 may indirectly induce M2-polarization through upregulating cytokines including IL10, CCL2 and CSF1 expression in tumor cells." (PMID 34583750, 2021). "Moreover, tumor-derived CCL2, CCL12, CXCL5, S100A8, and S100A9 promote the recruitment of immature myeloid cells to the tumor stroma, facilitating the enrichment of both MDSC subpopulations within the TME." (PMID 33430105, 2021). "Moreover, these cells can recruit MDSCs into the tumor microenvironment (TME) by releasing certain chemokines, such as CXCL5, CXCL8, CXCL12, CCL2, and CCL5." (PMID 35004667, 2021). "Further, CCL2 produced by MØs is required for metastatic seeding of cancer cells rather than tumor growth at the primary and metastatic sites." (PMID 34804061, 2021). "Interestingly, CCL2 expression is dramatically increased in BCSCs based on TCGA data set and we propose a hypothesis that secretion of CCL2 from BCSCs is enhanced by LDHA, which could recruit more CCR2-positive tumor associated macrophages (TAMs) to further maintained the stemness of BCSCs." (PMID 34178639, 2021). "In addition, CCR2 ligands including CCL-2, CCL-7 and CCL-12 were shown to be markedly higher expressed in tumor-infiltrating L-MSCs than in BM-MSCs." (PMID 34513701, 2021). "Furthermore, it has been reported that CCL2, IL10, and CSF1 not only expressed in tumor cells, but also in macrophages." (PMID 34583750, 2021). "On the other hand, CCL2/CCR2 has been shown to exert both pro- and anti-tumor effects." (PMID 34187403, 2021). "CCL2 levels are not always positively correlated with abundance of infiltrating Tregs; this varies according to the tumor type and inflammatory state." (PMID 34386431, 2021). "CCL2 can bind to its receptor CCR2 and play an important role in tumor development and metastasis by regulating tumor cell growth and survival, angiogenesis, tumor invasion, and metastasis." (PMID 33414423, 2021). "To evaluate the behavior of exosomes in such a cytokine milieu, we obtained exosome-depleted tumor interstitial fluid (TIF) from syngeneic, orthotopic EO771 cancer masses, which showed a range of cytokines and growth factors, including CCL2 and IL-6." (PMID 34112803, 2021). "The presence of chemokine C-C motif ligand 2 (CCL-2), or monocyte chemoattractant protein 1 (MCP-1), in the TME, produced by both tumour cells and stromal cells, has been shown to attract macrophages and subsequently maintain chemotaxis by stimulating these macrophages to also secrete CCL-2." (PMID 34452439, 2021). "Interestingly, a cascade involving CCL2 and CCL3 has been described, in which TAMs, derived from CCL2-recruited MDSCs, secrete CCL3, which further promotes macrophage retention in the tumor and tumor metastatic sites." (PMID 34575965, 2021). "Largely tumor derived, CCL2/MCP-1 exerts autocrine-mediated promotion of tumor growth and invasion, and paracrine-mediated recruitment of myeloid-derived suppressor cells (MDSCs) that enhance tumor cell survival." (PMID 34604038, 2021).
tumor (continued). "Factors that can promote the anti-tumor neutrophil phenotype include chemokines (e.g., CXCL2, CXCL5, CXCL8, CCL2, CCL3, CCL5, CXCL12 (SDF-1), CXCL16 and IL-8) alone or together with G-CSF/GM-CSF, TNFα, IFNβ, IFNγ, IFNγ together with TNFα, Resolvin D1, hepatocyte growth factor (HGF) and IL-17." (PMID 34572138, 2021). "The majority of mice bearing CCL2 KD tumors lacked macro-metastases in the lungs, and mainly presented with disseminated tumor cells, whereas mice with control A3250 tumors mainly presented with macro-metastases." (PMID 34824220, 2021). "EPCs are recruited into ischemic or hypoxic tumours predominantly in response to chemokines (e.g., CXCL12, CCL2, CCL5) and growth factors (e.g., VEGF, bFGF), which interact with their respective receptors (e.g., CXCR4, CCR2, CCR5, VEGFR2) on the surface of EPCs." (PMID 34035882, 2021). "Interestingly, while the upregulation in tumors is markedly higher for CCL4 and CXCL2, the CCL2, CCL8 and CCL19 transcripts are relatively downregulated in tumors compared to tumor-adjacent tissue." (PMID 34885960, 2021). "Moreover, coexpression of Cxcl1 and Ccl2 efficiently attenuated activation of CD8+ and CD4+ T cells in tumour cells ectopically expressing USP12, as evidenced by the changes in the frequencies of TNF-α+IFN-γ+ cells in the populations." (PMID 34381028, 2021). "There, tumor growth, macrophage recruitment, and tumor angiogenesis were not affected by CCL2 blockade." (PMID 33540898, 2021). "Moreover, cytokines and chemokines produced by cancer and stromal cells, such as TGF-β, IL-6 and CCL2, contribute to the recruitment and differentiation of immunosuppressive cells, which in turn further reduce CAR T cell potency in the tumor." (PMID 33588928, 2021). "CCL2 and C-C motif chemokine ligand 17 (CCL17) support tumour growth by recruiting CD4+ Treg cells and macrophages, while VEGF and MMP-9 stimulate angiogenesis and tumour cells migration." (PMID 34769447, 2021). "The key representative, MCP-1/CCL2, has previously been demonstrated to be upregulated in CRC at the local and systemic levels and induce the proliferation and epithelial-mesenchymal transition of tumor cells." (PMID 34884259, 2021). "Their recruitment to the tumors increases the interaction between estrogen receptors (ERs) and C–C Motif Chemokine Ligand 2 (CCL2), wherein CCL2 promotes epithelial-to-mesenchymal transition (EMT) and the production of matrix metalloproteinases (MMP) in the tumor location." (PMID 34829729, 2021). "The M1 macrophages produce pro-inflammatory factors (TNF-α, IL-1β, and iNOS), chemokines (CXCL10, CXCL11, and CCL2), antigen-presenting molecules such as MHCII, costimulatory molecules (CD86 and CD80), and antigen-treated peptidases, which play an anti-tumor role in cancer." (PMID 34034714, 2021). "Surprisingly, human CCL2 levels were significantly increased in both circulating blood and tumor interstitial fluid, whereas murine CCL2 levels were not affected." (PMID 33540898, 2021). "CCL2 was not directly involved in ccRCC cell proliferation in vitro, but tumor proliferation, angiogenesis, and macrophage infiltration were suppressed in CCL2-knockout mice." (PMID 34445235, 2021). "In the EPA group, 614 genes were identified as differentially expressed in tumor cells from patients with decreased CCL2 plasma levels compared to patients with no change or an increase in CCL2 plasma levels." (PMID 32498320, 2020). "Since CCL2 or P65 can be upregulated in infiltrating immune cells, we cannot rule out a contribution from the tumor microenvironment instead of only tumor cells." (PMID 32455851, 2020). "Application of a single cut-off for the staining status of tumor cells (TCs; positive vs. negative) and immune cells (ICs; ≤6% of ICs vs. >6% of ICs) revealed 57 cases (33.9%) and 70 cases (41.7%) with CCL2-positive TCs or ICs, respectively." (PMID 32429318, 2020).
tumor (continued). "Thus, expression patterns of Ccl2 and Ccr2 indicated that inflammatory signals were inhibited in the TRAMP-C1-derived tumor microenvironment." (PMID 32244522, 2020). "Furthermore, chemokines including CCL2 and CCL5 contribute to tumor proliferation through the formation of an immunosuppressive TME by recruiting Treg cells or inflammatory monocytes and macrophages." (PMID 31991604, 2020). "We found that CCL2, but not CSF-1 produced by tumor cells is highly expressed by high-grade lesions, thus highlighting the role of this chemokine in the recruitment of suppressive BMDMs." (PMID 32642721, 2020). "Additionally, blocking CCL2, or its receptor CCR2, reduces tumor growth and metastases, and this mechanism is currently being target in the clinic." (PMID 32528880, 2020). "Moreover, CCL2 and CXCL10 was present in the tumor and the tumor microenvironment and co-localized with almost all Nestin+, Iba-1+, CD163+ or CD16+ cells, suggesting the same distribution and localization." (PMID 32943658, 2020). "In collaboration with G–CSF, tumor cell-derived CCL2 educated neutrophils to migrate into pre-metastatic lung and to produce HOCl, thereby inhibiting breast cancer seeding to lungs, probably by acting on TRPM2 expressed in tumor cells." (PMID 32422991, 2020). "Additionally, chemokine signaling events such as CCL2/CCR2 signaling and CXCL11/CXCR7 signaling have been reported to play critical roles in tumor angiogenesis." (PMID 33099574, 2020). "TAMs participate in the tumour angiogenesis by secreting pro‐angiogenic factors, including VEGF‐A, EGF, PlGF, TGF‐β, TNF‐α, IL‐1β, IL‐8, CCL2, CXCL8 and CXCL12, and enable tumour metastasis by up‐regulated N‐cadherin and Snail, whereas down‐regulated E‐cadherin." (PMID 32588948, 2020). "The attraction of these Treg to the tumor microenvironment may be mediated by various mechanisms, including IDO activity and CCL2 production, which interacts with CCR4 at the surface of Treg." (PMID 32014107, 2020). "In our study plasma CCL2 levels peaked on day 7 and were markedly reduced at day 14 post-inoculation coinciding with changes in MDSCs within the tumor microenvironment, but not Tregs." (PMID 32240177, 2020). "Chemokines and their receptors play an important role in directing cognate T-APC interactions in lymph nodes and spleen (e.g., CCR7 and CCL21/19), or in bone marrow (e.g., CXCR4 and CXCL12 (SDF-1α/β), or attracting Treg cells towards tumor tissue (e.g., CCR2 and CCL2 (MCP-1))." (PMID 32155856, 2020). "According to the elevated expression of chemokine CCL2 in cancer cells and tumor tissues, we speculate CCR2 may correlate with tumor tropism of EVs as their donor cells." (PMID 32550891, 2020). "In addition, treatment with zoledronic acid (ZA) can reduce the expression of CCL2 in MSC cells, thereby reducing the recruitment of TAMs to the tumor site, thereby inhibiting tumor growth." (PMID 33224886, 2020). "Several cytokines and chemokines (e.g., GM-CSF, G-CSF, CCL2, CXCL1) induce the mobilization of MDSCs from bone marrow to the peripheral lymphoid organs and to the TME, where they promote tumor immune evasion through direct or indirect mechanisms, both antigen-specific and unspecific." (PMID 32823961, 2020). "Leukocyte recruitment to the tumor site is mediated by inflammatory chemokines from the CXC subfamily (CXCL1, -2, -5, -6, and -8) as well as from the CC group (CCL2, -3, and -5), which attract leukocytes: neutrophils bearing receptors CXCR2 and CCR2-positive monocytes." (PMID 32456359, 2020). "A negative correlation for the CCL2-positive IC percentage was detected with tumor stage (rs = −0.155; p = 0.045), lymph node stage (rs = −0.210; p = 0.006), and molecular subtype (rs = −0.336; p < 0.001)." (PMID 32429318, 2020). "Notably, galectin-1 is required for CCL2 expression in CAFs, promoting OSCC tumor growth and intravasation in xenograft models." (PMID 33363032, 2020).
tumor (continued). "In addition, combination treatment with a CCL2 antagonist and anti-PD1 antibody enhanced CD4+ and CD8+ T cell infiltration, as well as the production of IFNγ, and increased the survival time of tumor-bearing mice." (PMID 32005273, 2020). "Further, attempts to specifically target peripheral macrophages, for example limiting monocyte infiltration via Ccl2 genetic ablation, prolonged the survival of tumour-bearing mice, but these approaches have not been applied to patients yet." (PMID 31973030, 2020). "CCL2 expression was scored as positive vs. negative for TCs and as a percentage of CCL2-positive cells for ICs in the tumor cell area." (PMID 32429318, 2020). "Production of CCL2 was further enhanced in LKB1 reconstituted spheroid co-culture without tumor cell STING activity as compared to STING intact spheroid co-culture or vasculature alone." (PMID 33013881, 2020). "Therefore, in mouse HCC models, intratumoral injection of antibodies targeting CCL2 and CCL17 reduces the migration activity of macrophages and Treg cells, and delays tumor growth." (PMID 33224886, 2020). "Furthermore, interaction of cholangiocarcinoma cell-derived EVs with MSCs induces the expression of α-smooth muscle actin, CCL2, CXCL-1, IL-6 in the MSCs which in turn influence the proliferation of tumor cells via enhanced STAT3 phosphorylation." (PMID 32499786, 2020). "IFN-γ and other cytokines, such as CCL2, CCL23, CXCL9, and CXCL10 have anti-tumor roles." (PMID 32346605, 2020). "It was demonstrated that VE-cadherin expression and downstream activation of the Akt/GSK3β/β-catenin signaling caused an increase in the expression of the chemokine (C-C motif) ligand 2 (CCL2) and CXCL10, which facilitate CD8+ T cell transmigration into tumor parenchyma." (PMID 33276489, 2020). "M-MDSC and inflammatory monocytes are recruited to tumours through a CCL1, CCL2, and CCL5-induced chemokine cascade that is propagated by cancer cells and has been found to be retained within primary tumours by CCL3 produced via CCR-2 activated mechanism in metastasis-associated macrophages." (PMID 32121014, 2020). "Neutralizing CCL2, or its receptor CCR2, reduces tumor growth and metastases." (PMID 32528880, 2020). "Lastly, after the purified tumour-infiltrating PMN-MDSCs were cultured for 24 h in vitro, cells from the HSD group expressed more TNF-α and ICAM-1 and less prostaglandin E2 (PGE2), Arg1, CCL2 and CCL5 than those from the NSD group." (PMID 32265505, 2020). "FAK activity within CAFs regulates CCL2 mRNA and secreted protein expression, favours in vitro M2 macrophage polarization and migration, and positively correlates with CD206+ macrophage number within human PDAC tumours." (PMID 33025708, 2020). "Since we observed robust production of CCL2 in meningeal macrophages during PDAC, we hypothesized that tumor-derived factors could induce CCL2 or other chemokines in brain macrophages." (PMID 32391790, 2020). "Similarly, tumor tissue lysates and sera from LLC tumor-bearing KI mice also showed a significant reduction in circulating CCL2 levels, compared to WT controls." (PMID 32528880, 2020). "FAP positive CAF secrete high levels of CCL2 which in turn addresses the CCL2 receptor (CCR2) on circulating MDSC, activating immunosuppressive STAT3 signaling and leading to an enrichment of MDSC in tumor tissues." (PMID 32899119, 2020). "In addition, increased levels of CCL2, VEGF, and TGF-β1 were correlated to macrophage infiltrated areas with high vascularization and collagen deposits, which indicate further tumor progression." (PMID 32283687, 2020).
tumor (continued). "This implies that the mechanism in which CAFs protect tumor cells from FSS involves forming stable cell aggregates that can persist even when subjected to FSS over 1,000 dyn/cm2 along with the secretion of soluble factors such as CCL2, CCL7 and CXCL5." (PMID 32256977, 2020). "CCL2 synthesis by tumor cells, stromal and bone marrow osteoblasts, subsequently mediate tumorigenesis, metastasis and recruitment of inflammatory monocytes that express CCL2 receptor CCR2 to the tumor sites." (PMID 33062602, 2020). "EVs derived from DCs exposed to hyperthermia and stress contain increased amounts of heat shock proteins and chemokines (CCL2, CCL5, and CCL20) and as such, promote infiltration of tumor-attacking T cells and DCs into the tumor microenvironment of mice treated with these EVs." (PMID 32765528, 2020). "Here, we show that suppression of the CCL2/CCR2 and CXCL10/CXCR3 axes by celecoxib in the tumor and the tumor microenvironment might contribute to antitumor effects." (PMID 32943658, 2020). "Besides M‐CSF, the CC chemokines CCL2, CCL3, CCL4 and CCL5 are well‐recognized chemotactic factors for macrophage populations in the tumour." (PMID 33025708, 2020). "However, chemokines CCL2 and CCL8 can further promote tumor growth and angiogenesis by recruiting and activating tumor‐related macrophages." (PMID 32253815, 2020). "To date, various signaling pathways, including PGE2, CCL2, CSF-1, TGF-β, CXCL5, CXCL12, IL-1β, and IL-6, have been identified to be involved in the infiltration and activation of MDSCs in tumor microenvironment." (PMID 32824865, 2020). "Further work is required to delineate the roles of host-derived CCL2 and tumor-derived CCL2 in PCa tumorigenesis and metastasis, and to elucidate the downstream signaling molecules which mediate the effect of CCR2 signaling in tumor promotion." (PMID 32471499, 2020). "Additionally, targeting signalling of CCL2/CCR2 with a CCR2 antagonist was found to remarkably reduce TAM recruitment and polarization, thus enhancing the immunotherapeutic effect of tumour." (PMID 32910558, 2020). "CCL2 can also recruit T helper type 17 (Th17) and MSC into the tumor niche." (PMID 33182504, 2020). "In fact, CXCR4, SPP1, ACKR3, CCL2, PTGS2, CD274 (PD-L1), CXCL11 were upregulated while CCL28, CCR1, CCR7 were down regulated in both comparisons (blue boxes), suggesting this as a signature specific of the core region of the tumor." (PMID 33066172, 2020). "Overall, we revealed that imperatorin not only exerts “cell‐intrinsic” effects to inhibit tumor invasion and metastasis by directly targeting CREB1, but it also exerts “cell‐extrinsic” effects to suppress tumor angiogenesis by inhibiting CAFs‐secreted CCL2." (PMID 32832354, 2020). "The CCL2 required for recruitment of macrophages was overexpressed in HCC, and macrophages could be recruited to the tumor tissues effectively." (PMID 34138195, 2020). "Indeed, PTMs modifying both chemokines (i.e., C-C chemokine ligand 2 and 5, CCL2 and CCL5) and immune receptors (i.e., peptide-MHC complex, pMHC), damp both T lymphocyte migration toward primary tumor site and T cell activation and persistence, respectively." (PMID 32133298, 2020). "However, expression of other M1/M2 markers (such as CCL2, IL-10, and EGR2) was similar between XO ki and XDH ki tumor infiltrating macrophages." (PMID 31659168, 2019). "CCL2 can be released not only by TAM, but by EC, fibroblasts and tumor cells as well." (PMID 30680411, 2019). "CCL2 is required for TAM and MDSCs recruitment in the tumor microenvironment, suggesting that HOTAIR has a main role in the modulation of this process promoting tumor growth and metastasis." (PMID 31072041, 2019). "The first approach includes the elimination of TAM and monocyte accrual to the tumor site through the inhibition of mainly CSF-1/CSF-1R (Colony Stimulating Factor 1/ Colony Stimulating Factor 1 Receptor) and CCL2/CCR2 (C-C Motif Chemokine Ligand 2/ C-C Motif Chemokine Receptor 2) signaling axes." (PMID 31060337, 2019).